CD38 (CD38 molecule)
Diseases named in the same sentence as CD38 in open-access papers (continued):
Sharing a sentence is not in itself a finding about the gene and the disease.
acute myeloid leukemia (continued). "Human CSCs/CICs were first isolated from acute myeloid leukemia (AML) as CD34+CD38- cells." (PMID 27415781, 2016). "This problem has been outlined in acute myeloid leukemia (AML) where CD38+ cells (CD38 antibody-laden) may be cleared by the residual immune system of NOD/SCID mice." (PMID 25886184, 2015). "Correlating the CD38 mRNA counts with the results from flow cytometry resulted in a correlation coefficient of 0.53, similar to values of correlation coefficients found in a previous study on surface antigens in acute myeloid leukemia (AML) blasts." (PMID 26046539, 2015). "Genes higher in the podoplaninhigh population are expressed in bone marrow, in acute myelogenous leukemia and in stem progenitor cells CD34+ and CD38+." (PMID 25502694, 2014). "CD96 is a promising candidate as a leukemic stem cell (LSC)-specific antigen and is expressed on the majority of CD34+CD38− Acute myeloid leukemia (AML) cells, whereas only a few cells in the normal Hematopoietic stem cell (HSC)-enriched population express CD96 weakly." (PMID 22634835, 2012). "Acute myeloid leukemia (AML) is a clonal hematopoietic disorder characterized by the malignant transformation and abnormal proliferation of bone marrow-derived, self-renewing stem cells, or CD34+ CD38− myeloid progenitors." (PMID 37623484, 2023). "CD38 is known to be expressed on most (acute myeloid leukemia) AML cells, and its lack of expression on hematopoietic stem cells renders it as a potential therapeutic target for myeloid CML-BP." (PMID 36524116, 2022). "In acute myeloid leukemia (AML), Bonnet and Dick first detected cells having similar characteristics to normal hematopoietic stem cells with the same markers (CD34+ and CD38−) that were much more prone to developing leukemia, which were referred as leukemic stem cells (LSCs) or CSCs." (PMID 34051847, 2021). "In the early nineties, Dick and colleagues observed that most subtypes of acute myeloid leukemia (AML) could be engrafted reliably in immunodeficient mice and that leukemic engraftment could only be initiated from CD34+CD38− fractions." (PMID 31317205, 2019). "In 1994, John Dick and colleagues reported in their historical work that human acute myeloid leukemia is organized in a hierarchical differentiation model, and CD34+CD38− cells are the stem cells of this model and only CD34+CD38− cells can regenerate the disease." (PMID 28415561, 2017). "His results showed that a subtype of acute myeloid leukemia (AML) was able to reconstitute tumors in immune-compromised mice, but most importantly, these cells were isolated from a specific fraction (i.e. CD34+CD38−)." (PMID 27158195, 2015). "It has been demonstrated that brain, colon, prostate and lung CSCs bear the antigen CD133, while ovarian CSCs are CD24+ and CD133+, acute myeloid leukemia stem cells are CD34+ and CD38−, head and neck CSCs are CD44+, B-precursor acute Lymphocytic leukemia CSCs are CD34+, CD38+ and CD19+." (PMID 26184171, 2015). "Interestingly, this innovative treatment does not significantly affect healthy B lymphocytes nor a negative control cancer cell line, a CD38- acute myeloid leukemia, being thus highly specific and targeted." (PMID 38353903, 2024). "CSCs were first identified in acute myeloid leukemia (AML); the study demonstrated that AML CSCs with the phenotype CD34+ CD38− constituting approximately 0.1–1% of the tumor population, can generate AML in mice." (PMID 36768150, 2023). "In patients with acute myeloid leukemia (AML), Bregs are categorized as CD19+, CD24+, and CD38+, and the presence of these cells is correlated with poor prognosis." (PMID 35746487, 2022). "They found that the cytotoxic potential of CD38 KO-CD38 CAR-NK cells was augmented and proposed a viable immunotherapeutic approach for the treatment of acute myeloid leukemia (AML)." (PMID 36324149, 2022).
acute myeloid leukemia (continued). "CD38 is expressed in hematological malignancies, including acute B lymphoblastic leukemia (B-ALL), acute myeloid leukemia (AML), mantle cell lymphoma (MCL), CLL, multiple myeloma (MM) and NK/T cell leukemia (T-ALL)." (PMID 34421911, 2021). "Although the applicability of CD19-directed CAR-T therapy in acute myeloid leukemia (AML) is limited, alternative leukemic cell-specific antigens such as CD33, CD38, CD56, CD117, CD123, Lewis-Y, and Muc-1 are currently being explored." (PMID 34203935, 2021). "In a very recent study performed on acute myeloid leukemia (AML) patients, Bregs are defined as CD19+ CD24+ CD38+." (PMID 31086070, 2019). "By using fluorescence activated cell sorting (FACS) based on CD34 and CD38 (CD34+ CD38−) surface marker expression, John Dick isolated the first CSCs from acute myeloid leukemia (AML)." (PMID 30728463, 2019). "A CSC model was first suggested in Acute Myeloid Leukemia (AML), where only a rare population of CD34+ CD38- cells in the peripheral blood collected from AML patients could engraft in immunodeficient mice and recapitulate morphological features of the original malignancy." (PMID 24212622, 2011). "CSCs were first identified in acute myeloid leukemia (AML) after transplanting isolated CD34+/CD38− cancer cells into non-obese diabetic/severe combined immunodeficient (NOD/SCID) mice." (PMID 41190163, 2025). "Expression of CD38 has been found in chronic lymphocytic leukemia (CLL), acute lymphoblastic leukemia (ALL), acute myeloid leukemia (AML), aggressive natural killer (NK) cell leukemia (ANKL), NK/T-cell lymphoma, mantle cell lymphoma (MCL), and Waldenström’s macroglobulinemia (WM)." (PMID 37760502, 2023). "As a transmembrane glycoprotein, CD38 is expressed in T-ALL and acute myeloid leukemia (AML) cells." (PMID 37108359, 2023). "Notably, a study has been performed on acute myeloid leukemia (AML) where B cells include a higher proportion of regulatory B cells and display surface markers CD19, CD24, and CD38." (PMID 31684152, 2019). "For example, in acute myeloid leukemia (AML), CSCs populations are CD34(+) CD38(−)." (PMID 29907133, 2018). "In contrast, the selectivity towards a negative control cancer cell type, i.e. acute myeloid leukemia (HL60 cell line), not expressing CD38 antigen, does not occur." (PMID 38353903, 2024). "A study reported that Ventx was aberrantly expressed in CD34+ acute myeloid leukemia (AML), and its maximum expression was found in CD33+ myeloid cells but not in normal CD34+/CD38− leukemic cells." (PMID 35269883, 2022). "In contrast to other tested antigens co-expressed on chronic myeloid leukemia (CML) LSCs, acute myeloid leukemia (AML) LSCs and normal HSCs, CD26 is the only marker which is not present in CD34+/CD38− normal stem cells." (PMID 39000199, 2024).
lymphoma (77 papers, 1995 to 2025). A malignant (clonal) proliferation of B- lymphocytes or T- lymphocytes which involves the lymph nodes, bone marrow and/or extranodal sites. "To confirm that anti-CD38-IFNα(att) retains robust anti-tumor activity in vivo despite its attenuating mutation, we tested its activity in CD38 positive human MM and lymphoma xenograft tumor models." (PMID 27611189, 2016). "In particular, a fragmented anti-CD38 (the clinical-grade Daratumumab) is employed to drive the nanoconstruct against CD38 antigen overexpressed by Burkitt’s Lymphoma cells." (PMID 38353903, 2024). "In the light of these findings, we analysed online gene expression data sets of pBL samples and compared them with other paediatric lymphomas to investigate the CD38 gene expression profile and its correlation with MYC gene expression." (PMID 39364393, 2024). "We compare two monoclonal antibodies targeting CD38, finding isatuximab more effective than daratumumab in reducing cell proliferation, inducing apoptosis and impacting key survival pathways in lymphoma cells." (PMID 39364393, 2024). "The expression of CD38 in lymphoma, together with preclinical evidence for anti‐CD38 antibodies against CD38+ lymphoma, suggests potential utility for these agents in patients with CD38+ lymphoma." (PMID 36251503, 2023). "CD38+/CD20+ mantle cell lymphoma (MCL) GRANTA-519 cells or lymphoma cells freshly isolated from two MCL patients were used as target cells." (PMID 37965326, 2023). "We first demonstrated that CD38-CAR T cells have robust anti-tumor function against CD38high lymphoid cancer cells." (PMID 35765110, 2022). "Collectively, these data support the potential clinical utility of ATRA with daratumumab or CD38-CAR T cells against CD38low lymphoid cancer cells, especially MCL cells." (PMID 35765110, 2022). "We generated chimeric antigen receptor (CAR) T cells targeting CD38 and tested its cytotoxicity against multiple CD38high and CD38low lymphoid cancer cells." (PMID 35765110, 2022). "Daratumumab targeting CD38 can lyse lymphoma cells or CD38+ immunosuppressive cells through Fc-mediated complement-dependent cytotoxicity (CDC), ADCC, and Ab-dependent cellular phagocytosis (ADCP)." (PMID 35464486, 2022). "In vitro binding of nanobody JK36AF680 to daratumumab-pretreated cells was assessed using five human (LP-1, U266, RPMI-8226, CA46, Daudi) lymphoma cell lines, and one murine lymphoma cell line transfected with human CD38 (YAC-1 CD38+)." (PMID 36389758, 2022). "A fluorescent-labelled sdAb recognized CD38+ tumor cells in flow cytometry assays and were subsequently used for in vivo imaging of CD38+ lymphoma cells." (PMID 35865548, 2022). "For example, we have recently shown that human CD38-specific hcAbs can be used to effectively target human MM cells in xenograft mouse models of systemic human lymphoma." (PMID 34539634, 2021). "Based on the commercial availability and clinical application of daratumumab, radiolabeled daratumumab can provide a personalized approach that would be widely available for CD38‐positive lymphomas, especially MM." (PMID 34026426, 2021). "These human CD38-specific hcAbs reduced the growth of a systemic lymphoma and prolonged the survival of tumor bearing SCID mice." (PMID 34539634, 2021). "We investigated the effects of lipid depletion followed by repletion on Saponinum album (SA)-induced endolysosomal escape of Alexa Fluor labelled saporin and the saporin-based immunotoxin OKT10-SAP, directed against CD38, in Daudi lymphoma cells." (PMID 33228031, 2020). "A similar role for CD38 as prognostic marker was reported for extranodal natural killer/T cell lymphoma (ENKTL), an Epstein-Barr virus associated lymphoma relatively rare in western countries, but more diffuse in the Asian area." (PMID 31636635, 2019). "Isatuximab was selected because of its direct induction of apoptosis in CD38-expressing lymphoma cell lines, in addition to its multiple effector cell-dependent cytotoxicity." (PMID 31548533, 2017).
lymphoma (continued). "To this end we used a two-sided tumor model in nude mice bearing untransfected and CD38-transfected lymphoma cells injected subcutaneously in the left and right flanks." (PMID 29084989, 2017). "Daratumumab demonstrated superior induction of CDC in Daudi lymphoma cells as determined by flow cytometry, when compared with other CD38 antibodies in current clinical development." (PMID 31548533, 2017). "The lymphoma cells mostly express plasmacytic markers such as CD38 (100%), MUM1 (100%) and CD138 (84%)." (PMID 25613729, 2015). "The histopathologic features of PBL include the presence of a high grade lymphoma comprised of plasmablasts that stain positive for plasma cell markers such as CD38, VS38c, MUM1, and CD138." (PMID 24371535, 2013). "The best method to differentiate EMP from other types of plasma cell tumors or lymphomas is that the EMP is positive for CD38 and monoclonal cytoplasmic light chain expression of malignant plasma cells obtained by surgical or needle biopsy." (PMID 17963517, 2007). "However, CD38 is also expressed in diseases other than MM, such as chronic lymphocytic leukemia, acute leukemia, and various lymphomas (follicular cells, mantle cells, and diffuse large B-cell lymphomas)." (PMID 38983860, 2024). "Because a subset of lymphomas express CD38, including the majority of ENKTL cases, targeting CD38 with radioisotopes could provide both diagnostic and therapeutic benefits." (PMID 39456582, 2024). "Thus, the opportunity remains to develop regimens that incorporate an anti‐CD38 monoclonal antibody as a partner for patients with lymphoma." (PMID 36251503, 2023). "To address whether co‐inhibition of PD‐1 and CD38 may benefit patients with lymphoma, we assessed the safety, efficacy, and pharmacokinetics of Isa + Cemi in patients with cHL, DLBCL, and PTCL." (PMID 36251503, 2023). "We examined the effects of various doses of ATRA on CD38 expression in lymphoid cancer cells." (PMID 35765110, 2022). "This work lends support to the use of ATRA and anti-CD38 immunotherapies against lymphoid cancers." (PMID 35765110, 2022). "Thus, our data broaden the potential clinical use of anti-CD38 immunotherapies to treat CD38high lymphoid cancer cells and support the combinations with ATRA to treat CD38low cancers that are sensitive to ATRA." (PMID 35765110, 2022). "CD38, a 45 kDa transmembrane glycoprotein receptor, is highly expressed on 95–100% of malignant plasma cells and at relatively low levels on normal cells, presenting a promising biomarker for several types of lymphomas, particularly MM." (PMID 34026426, 2021). "As the diagnostic component, the Zr‐89‐labeled mAb is highly specific in delineating CD38‐positive lymphoma via positron emission tomography imaging, while the Lu‐177‐labeled mAb serves well as the therapeutic component to suppress tumor after a one‐time administration." (PMID 34026426, 2021). "Herein, a potential marker, CD38, is investigated for differentiating lymphoma." (PMID 34026426, 2021). "As the diagnostic component, the Zr‐89‐labeled mAb is highly specific in delineating CD38‐positive lymphoma via positron emission tomography (PET) imaging, while the Lu‐177‐labeled mAb serves well as the therapeutic component to suppress tumor growth after a one‐time administration." (PMID 34026426, 2021). "Further clinical evaluation and translation of this CD38‐targeted theranostics may be of significant help in lymphoma patient stratification and management." (PMID 34026426, 2021). "Moreover, the DH-My6 cells show strong CD38 expression, which appears to be a characteristic phenotype of lymphomas with MYC rearrangement." (PMID 30323893, 2018). "CD38-specific nanobodies were selected by binding of phages to CD38-transfected lymphoma cells." (PMID 29084989, 2017). "Finally, Daudi lymphoma tumors were highly responsive to IFNα AttenukineTM indicating that anti-CD38-IFNα(att) is likely a strong therapeutic candidate for multiple types of CD38-positive lymphoid cancers." (PMID 27611189, 2016).
lymphoma (continued). "However, the strong and diffuse expression of TdT, low proliferation index by ki-67, and bright CD38 by flow cytometry favor a diagnosis of an immature precursor B-cell leukemia/lymphoma." (PMID 23533894, 2013). "In both lymphoma patients and HC, unsupervised cluster analysis showed that levels of naïve T cell populations correlated with the level of induced antibody responses (cluster 2, r = 0.6, p < 0.0001, cluster 11 (CD38+, ICOS+), r = 0.5, p = 0.01, and cluster 3, r = 0.3, p = 0.007)." (PMID 40630518, 2025). "Also, CD38 expression should have been tested on lymphoma tissue as well as bone marrow." (PMID 35106962, 2022). "Compared to HC, lymphoma patients -except those treated with CT alone – showed higher representation of more differentiated cytotoxic CD8 + EMRA subsets, expressing CD38 (cluster 6, 7)." (PMID 40630518, 2025). "One approach to address this problem is to use dual-targeting CAR T cells, as observed in clinical trials using CAR T cells targeting CD19/CD22 for leukemia and lymphoma, CD19/CD20 for lymphoma, and BCMA/CD38 for MM11–15." (PMID 38643278, 2024). "Overall increased metabolic fitness was accompanied by the monocytes’ superior ability to ingest MM and lymphoma cell lines that are co-treated with anti-CD20 and anti-CD38 antibodies, respectively." (PMID 34021248, 2021). "In line with their metabolic and transcriptomic profile, CD137HI monocytes displayed a superior phagocytic capacity in terms of bacterial pathogens as well as lymphoma or MM cell lines that were pretreated with anti-CD20 and anti-CD38 mAbs." (PMID 34021248, 2021). "Similar results were observed in B-cell non-Hodgkin lymphoma (B-NHL) cell lines, in primary cells from lymphoma patients, and in lymphoma NOD/SCID mice models, in which CD38-CAR efficiently eradicated tumor cells." (PMID 34203935, 2021). "The lymphoma cells usually expressed CD45, markers of lymphocyte activation (CD30, CD38, EMA, HLA-DR) and markers of plasma cell differentiation (CD138, MUM1/IRF4)." (PMID 33906629, 2021). "At the immunohistochemical level, it has been found that CD38 and CD44 can be used to distinguish between MYC-positive and MYC-negative lymphomas." (PMID 31484540, 2019). "We found that all of the lymphoma samples consistently expressed B220, CD24, CD38, CD43, CD93, and CD138." (PMID 26740101, 2016). "Flow cytometry revealed a different population of lymphoma cells, this time positive for CD5, CD19, CD20, and CD22, with dim expression of CD45 and CD38." (PMID 27957358, 2016). "In our study, two patients were treated with the CD38-targeting antibody Daratumumab and exhibited sufficient antibody production; nevertheless, there was one Daratumumab-treated lymphoma patient who did not respond to the vaccination." (PMID 41050077, 2025). "We compared CD38 expression levels across a panel of cell lines representing various hematological malignancies and found that the AML cell line Molm13, lymphoma cell lines Nalm6 and Raji, and T-ALL cell lines CCRF-CEM and Molt4 exhibited particularly high CD38 expression." (PMID 39856752, 2025). "Lymphoma cells highly expressing CD38 respond well to CD38-CAR T, and those dimly expressing CD38 could be re-sensitized to CD38-targeted therapy by all-trans retinoic acid or panobinostat." (PMID 38711850, 2024). "When we examined expression data for additional ATCC parental cancer cell lines without already existing luciferase reporters, we found that the lymphoma cell lines Raji, Farage, and Daudi express high levels of CD19, as well as high levels of CD20, CD22, and CD38." (PMID 39061136, 2024). "Furthermore, findings from another study indicated that high CD38 protein expression is a significant indicator of MYC rearrangement in high‐grade B‐cell lymphomas, a category that includes aggressive lymphomas such as BL." (PMID 39364393, 2024).